HMOX1 (heme oxygenase 1)
Diseases named in the same sentence as HMOX1 in open-access papers (continued):
Sharing a sentence is not in itself a finding about the gene and the disease.
cardiovascular diseases (continued). "The enriched HMOX1 variants in the African population are associated with lower levels of HO-1 expression, which may contribute to a higher risk of HDP and other cardiovascular diseases." (PMID 35697922, 2022). "Moreover, the cardioprotective effect of HOMX1 has been verified in simulated H9C2 cells in vitro, and the latest study explored the relationship between HMOX1 and cardiovascular disease from the perspective of ferroptosis." (PMID 35915792, 2022). "Moreover, it has recently reported a beneficial effect of heme oxygenase-1 (HO-1)/adiponectin axis on cardiovascular disease." (PMID 31261958, 2019). "Some studies revealed that shorter GT repeats in the hmox-1 promoter region are associated with lower incidence and/or progression of CAD, whereas others argue against a relevant role of this polymorphism in cardiovascular diseases." (PMID 24847266, 2014). "Nevertheless, neither the (GT)n dinucleotide repeat nor the -413A>T polymorphism of HMOX1 gene are reliable genetic markers for cardiovascular disease in Caucasians." (PMID 19389234, 2009). "Target genes of NRF2, such as heme oxygenase-1 (HO-1) or superoxide dismutase (SOD), play a protective role in the pathogenesis of cardiovascular diseases." (PMID 34054535, 2021). "HMOX1, PDGFB, Ins, VEGF, and STAT5B are key nodes in the “Cardiovascular Disease, Lipid Metabolism, Molecular Transport” network and also interact with other DE genes." (PMID 25774290, 2015). "Serum bilirubin levels, which are determined by a complex interplay of various enzymes, including heme oxygenase-1 (HO-1) and uridine diphosphate–glucuronosyl transferase (UGT1A1), may be protective against progression of cardiovascular disease (CVD) in hemodialysis patients." (PMID 34573035, 2021).
neurodegenerative disease (97 papers, 2007 to 2026). A disorder of the central nervous system characterized by gradual and progressive loss of neural tissue and neurologic function. "In neurodegenerative diseases like Alzheimer’s, benfotiamine activates the transcription factor Nrf2, leading to increased expression of genes encoding antioxidant enzymes such as heme oxygenase 1 (HO-1) and quinone reductase 1 (NQO1)." (PMID 40647310, 2025). "Moreover, HMOX1 deregulation has been associated with the development of neurodegenerative diseases, including AD." (PMID 33096789, 2020). "Heme oxygenase 1 (HO-1) has a large number of antioxidant elements, making it a potential therapeutic target for the prevention of neurodegenerative diseases." (PMID 36080395, 2022). "Nrf2-related/heme oxygenase 1 (Nrf2/HO-1) is an important signaling pathway that plays an important role in inflammatory-derived diseases such as liver damage and neurodegenerative disease." (PMID 35648353, 2022). "Heme oxygenase-1 (HMOX1) is a redox-regulated enzyme that is induced in neurodegenerative diseases and acts against oxidative stress but can also promote cell death, a phenomenon that is still unexplained in molecular terms." (PMID 33691741, 2021). "It is well established that HMOX1 can play beneficial as well as detrimental roles in neurodegenerative diseases." (PMID 33691741, 2021). "The heme metabolism in the brain seems to be impaired in neurodegenerative diseases as documented by elevated expression of HMOX1 in these pathologies (, see also below)." (PMID 32971784, 2020). "Heme oxygenase-1 (HO-1), combined with potent AREs in its promoter, is a highly effective therapeutic target for the protection against neurodegenerative diseases, including I/R-induced retinal damage." (PMID 24400114, 2014). "For example, heme oxygenase-1(HO-1), as one of critical downstream molecule of Nrf2, was found to regulate oxidative stress in a range of diseases, such as neurodegenerative disease and in LPS-stimulated RAW 264.7 macrophages." (PMID 25485090, 2014). "Furthermore, this corroborates the data regarding the protective role of both Nrf2 and HMOX1 induction, demonstrated in several cell and animal models of neurodegenerative diseases." (PMID 33096789, 2020). "Notably, heme oxygenase-1 (HO-1) is beneficial in various diseases, especially neurodegenerative diseases such as AD." (PMID 28173812, 2017). "In addition, madecassoside significantly increased the gene expression of the anti-inflammatory component heme oxygenase 1 (HO−1) by 175.22% compared to the LPS group, suggesting that this compound is an important ally in the treatment of neurodegenerative diseases." (PMID 33299526, 2020). "Based on the findings from in vivo and in vitro studies, both HMOX1 and FADD genes are considered promising therapeutic targets for neurodegenerative diseases." (PMID 41203125, 2025). "Nrf2 activation initiates phase II enzymes expressions, such as heme oxygenase-1 (HO-1) and NADPH quinone oxidoreductase 1 (NQO1), which mitigates the pathogenesis of neurodegenerative diseases." (PMID 31010422, 2019). "Interestingly, neuroprotective curcumin, by inducing Nrf2 and vitagenes including Hsp32 (HO-1/HMOX1), Hsp70 and thioredoxin system and by inhibiting NF-κB activation, prevents neurodegenerative diseases." (PMID 32046944, 2020).
kidney disease (70 papers, 2009 to 2025). "The associations between HMOX1 promoter polymorphisms and clinical outcomes were also observed among patients with other forms of kidney disease, such as renal transplantation, diabetic kidney disease and sickle cell nephropathy." (PMID 30597982, 2018). "It is likely that the serum HO-1 concentrations may merely reflect the presence of cardiovascular or kidney disease, whereas the HMOX1 polymorphisms may influence cardiovascular outcomes independently of the serum HO-1 concentrations." (PMID 40826355, 2025). "PD1 has also been shown to have renoprotective and antioxidant effects in CKD, in particular, acting on the heme oxygenase-1 (HO-1) pathway, which has been shown to be protective both in rodent and in human kidney disease models." (PMID 40243751, 2025). "Besides, increasing evidence found that heme oxygenase-1 (HO-1) has a cytoprotective role in renal disease." (PMID 34681895, 2021). "Heme oxygenase-1 (HO-1), one of the targets of Nrf2-ARE, plays an important role in regulating OS and is protective in a variety of human and animal models of kidney disease." (PMID 33562389, 2021). "Heme oxygenase 1 (HO-1), also referred to as heat shock protein (HSP) 32, has a key role in the amelioration of oxidative stress-related pathologies, including cardiovascular, lung, neurological, and kidney disorders." (PMID 29065463, 2017).
metabolic disease (48 papers, 2011 to 2026). A congenital disorder (due to inherited enzyme abnormality) or acquired (due to failure of a metabolically important organ) disorder resulting from an abnormal metabolic process. "Severe hypothermia causes metabolic disorders in cerebral cortex nerve cells, significantly altering ferroptosis-related genes such as PPARG, SCD, ADIPOQ, SAT1, EGR1, and HMOX1." (PMID 39125656, 2024). "Antioxidants have also been shown to exert protective effects on cardiovascular and metabolic diseases through anti-inflammatory actions, such as heme oxygenase-1 (HMOX1)." (PMID 38891996, 2024). "Despite the important role of oxidative stress in metabolic diseases, the associations of HMOX1 and NQO1 with MetS have not yet been thoroughly studied." (PMID 25933176, 2015).
inflammation (40 papers, 2012 to 2026). Aberrant reaction of the microcirculation characterized by movement of fluid and leukocytes from the blood into extravascular tissues. "However, microbiota imbalances and infections are also important factors influencing the occurrence of acute and chronic intestinal inflammation, where HMOX1 activity may play a major role." (PMID 30258436, 2018). "It has been shown that HMOX1 activity and the by-product CO can downmodulate the damaging immune response in several models of intestinal inflammation as a result of pharmacological induction of HMOX1 expression and the administration of non-toxic amounts of CO." (PMID 30258436, 2018).
liver (39 papers, 2011 to 2026). "In various acute and chronic liver injury models in mice, IL-22 has been shown to reduce hepatocyte damage and enhance liver regeneration by upregulating the expression of antioxidant and anti-apoptotic genes, such as heme oxygenase-1 (HO-1) and B-cell lymphoma-extra large (Bcl-xL)." (PMID 40399593, 2025). "IPC over-induced heme oxygenase-1 (HO-1) can protect fatty liver from IR injury, and the protective effect of IPC is weakened after using HO-1 inhibitors." (PMID 35572532, 2022). "Forsythoside A was also found to upregulate the expression of Nrf2 and heme oxygenase 1 in lipopolysaccharide-stimulated BV2 microglia cells and primary microglia cells, as well as, in vivo in a liver injury model." (PMID 33578811, 2021).
neurological disorders (32 papers, 2014 to 2025). "Chloride intracellular channel 1 (CLIC1) and the nuclear factor erythroid-related factor 2 (Nrf2)/heme oxygenase-1 (HO-1) pathway have been implicated in many neurological disorders." (PMID 40966238, 2025). "However, the activation of HMOX1 is followed by the increase of its side products, including iron, which will add more harm to already pre-existing HMOX1 hyper-activation in several neurological diseases." (PMID 37627520, 2023). "Oxidative stress and reactive oxygen species are well-researched contributors to ALS pathogenesis, and small molecule modulators to promote the Nrf2 and Hmox1 signaling pathway are being explored in ALS and other neurological diseases." (PMID 38015828, 2023).
bacterial infection (26 papers, 2010 to 2025). "It is well described that Hmox1 has an immunomodulatory function in bacterial infections, both in vitro and in vivo." (PMID 35739937, 2022). "Although little is known about the exact effect of Hmox1 on general bacterial infections, it has been shown that Hmox1 plays a role in the clearance of Salmonella by the immune system and that this effect is exerted by CO." (PMID 35739937, 2022). "Carbon monoxide (CO) has been proposed as the responsible for the bactericidal effect of Hmox1 in several bacterial infection models and is even considered a therapy." (PMID 35739937, 2022). "Although little is known about the exact effect of HMOX1 on bacterial infections, it has been described that HMOX1 plays a role in the clearance of Salmonella by the immune system." (PMID 30258436, 2018). "TLR9 activation provides protection against bacterial infections and Heme oxygenase-1 (HO-1) is known to enhance host innate immunity against bacterial infections." (PMID 28052108, 2017). "Mechanistically, during the early stages of bacterial infection, cells elevate unstable intracellular iron levels by activating two iron metabolism pathways: nuclear factor erythroid 2–related factor 2/heme oxygenase-1 (Nrf2/HO-1) and ferritin/NCOA4." (PMID 38965216, 2024). "In addition to the important effect of Hmox1 activity and its products in controlling inflammatory diseases and bacterial infections, porphyrins alone have also been studied as possible treatments for bacterial infections." (PMID 35739937, 2022). "Moreover, it has been demonstrated that CO can interact directly with heme groups of the bacterial electron transport chain, suggesting that HMOX1 has an effect in bacterial infections not only through the modulation of the immune response, but by the direct interaction with the pathogen." (PMID 30258436, 2018).
infectious disease (15 papers, 2012 to 2023). A disorder directly resulting from the presence and activity of a microbial, viral, or parasitic agent in humans. "A search using relevant terms was performed in PubMED and EMBASE through to 15/01/21 identifying all research that studied an association between the HMOX1 GT(n) repeat polymorphism and the incidence and/or outcome of any human infectious disease." (PMID 35551540, 2022). "Therefore, based on the data collected so far, we cannot conclude whether HMOX1 polymorphisms have a role in infectious disease." (PMID 35551540, 2022). "In humans, a polymorphism in the Hmox1 promoter result in differential expression of HO-1 such that individuals with fewer (GT)n repeats in the Hmox1 promoter transcribe more HO-1 in response to various stimuli, resulting in enhanced protection from both infectious and non-infectious diseases." (PMID 23244630, 2012). "The potential of Hmox1 and its derivatives as a treatment or target to treat inflammatory and infectious diseases has been widely discussed, and the data presented herein highlight this potential." (PMID 35739937, 2022). "Nuclear factor erythroid 2-related factor 2 (Nrf2) and heme oxygenase-1 (HO-1) have significant roles in the development of a hyperinflammatory state in infectious diseases." (PMID 36422196, 2022). "A third potential mechanism of hepatic ALAS1 up-regulation is associated with the inducible and highly dynamic heme oxygenase-1 (HMOX1, EC 1.14.14.18), which produces an active hepatic heme turnover in response to cell stress or inflammatory and infectious diseases." (PMID 33807619, 2021). "Heme oxygenase-1 production is induced during the course of several infectious diseases as well as inflammatory disorders and may play beneficial or detrimental role for the host depending on the stimulus and context." (PMID 28553288, 2017).
hematological malignancies (14 papers, 2005 to 2025). "However, unlike hematologic malignancies, adaphostin initiated an antioxidant response in NCI-H522 cells through up-regulation of HMOX1." (PMID 20618971, 2010).
immune diseases (10 papers, 2013 to 2025). "Heme oxygenase 1 induction has been suggested as a therapeutic approach to ameliorate self-directed immune diseases, including both autoimmune and autoinflammatory diseases." (PMID 32849503, 2020).
retinopathy (9 papers, 2016 to 2023). "In retinopathy, the protective or damaging effect of HMOX1 on the retina depends on the expression of HMOX1." (PMID 36689408, 2023). "In aged retinas, there is an increase in pro-inflammatory molecules and a decline in Nrf2 and heme oxygenase-1 (HO-1), suggesting poor protective response to oxidative stress, which may play a role in the pathogenesis of retinopathies." (PMID 34638620, 2021).
gastrointestinal disease (8 papers, 2008 to 2022). A disease that occurs in the gastrointestinal system, excluding the hepatobiliary system. "Previous studies have demonstrated that heme oxygenase-1 (HO-1) is an inducible antioxidant enzyme that exhibits a wide range of adaptive responses and represents a therapeutic target in the fight against oxidative stress and gastrointestinal diseases." (PMID 26610474, 2015).
heart disease (8 papers, 2014 to 2026). "Moreover, the heart protection and therapeutic effects of higenamine on heart disease are related to regulating LKB1/AMPKα/Sirt1, mediating the β2-AR/PI3K/AKT cascade, induction of heme oxygenase-1, suppressing TGF-β1/Smad signaling, and targeting ASK1/MAPK (ERK, P38)/NF-kB signaling pathway." (PMID 35082678, 2021).
brain diseases (7 papers, 2016 to 2025). "Heme oxygenase-1 or HO-1 (HMOX1) is a stress-sensitive enzyme that catalyzes the breakdown of heme into iron, carbon monoxide, and biliverdin/bilirubin and is involved in the pathobiology of AD and other brain disorders." (PMID 36225186, 2022).
blood cancers (4 papers, 2020 to 2024). "Interestingly, the expression levels of most FRGs, including SLC38A1, SLC11A2, and HMOX1, were found to be lower in CML samples compared to other types of hematologic tumors." (PMID 39026664, 2024).
respiratory diseases (4 papers, 2019 to 2024). "Research has revealed that the nuclear factor erythroid 2-related factor 2/heme oxygenase 1 (Nrf2/HO-1) signaling axis is involved in pediatric respiratory diseases." (PMID 31827672, 2019).
central nervous disease (3 papers, 2014 to 2024). "Impaired HMOX1 activity caused by genetic variants could modify the intraneuronal production of biliverdin/bilirubin metabolites which exert an antioxidant role contributing to the etiology of PD and other central nervous system disorders." (PMID 25309329, 2014). "Increasing evidence suggests the protective role of the Nrf2-ARE signal pathway in central nervous diseases mediated by heme oxygenase-1 (HO-1) and NQO1." (PMID 38167027, 2024).
intestinal disease (3 papers, 2016 to 2024). "Heme oxygenase-1 (HO-1) is expressed in the epithelial cells to impair the pro-inflammatory factors and oxidative stress in intestinal disease models." (PMID 35205169, 2022).
head and neck tumors (2 papers, 2020 to 2021). "In the clinic, we analyzed HO-1 gene (HMOX1) expression data obtained from The Cancer Genome Atlas (TCGA) and found that significantly lower HMOX1 transcripts were observed in head and neck tumors, compared to normal tissues." (PMID 32188144, 2020).
HMOX1 also shares sentences with these, for which no sentence is quoted: kidney injury (23 papers); hyperlipidemia (16); oral squamous cell carcinoma (16); acute myocardial infarction (15); infarction (14); Parkinson’s (14); neuropathic pain (12); vasculopathy (11); allergic rhinitis (10); astrocytoma (10); atopic dermatitis (10); autoimmune hepatitis (10); atrial fibrillation (9); lupus nephritis (9); adenocarcinoma (8); benign prostatic hyperplasia (8); idiopathic pulmonary fibrosis (8); nephritis (8); alcoholic liver diseases (7); amyotrophic lateral sclerosis (7); brain tumors (7); clear cell renal cell carcinoma (7); endometrial cancer (7); head and neck squamous cell carcinoma (7); IgA nephropathy (7); Kaposi's sarcoma (7); neurotoxicity (7); polycystic ovary syndrome (7); rhabdomyolysis (7); brain edema (6).
A further 402 diseases each share a sentence with HMOX1 in 6 papers or fewer.